SCUBE1 (signal peptide, CUB domain and EGF like domain containing 1)
Description:
Could function as an adhesive molecule and its matrix bound and soluble fragments may play a critical role in vascular biology.
Tractability: Antibody: UniProt places it where antibodies can reach, with high confidence; its Gene Ontology location is reachable by antibodies, with high confidence; UniProt predicts a signal peptide or a membrane-spanning region. PROTAC: ubiquitination databases record sites on it.
Gene: Protein-coding gene on chromosome 22 (43,197,280 to 43,343,375, reverse strand). Ensembl gene ENSG00000159307.
Subcellular location: Secreted; Cell membrane
Pathways (Reactome):
Extracellular matrix organization: Degradation of the extracellular matrix
Gene Ontology:
Molecular function: identical protein binding; protein binding; calcium ion binding
Biological process: adult heart development; blood coagulation; endothelial cell differentiation; inflammatory response; post-embryonic development; signal transduction
Cellular component: cell surface; external side of plasma membrane; extracellular region; plasma membrane
Genetic constraint (gnomAD): Loss-of-function variants: 58 observed, 111.14 expected, observed/expected ratio (o/e) 0.52, 90% interval 0.42 to 0.65. The upper end of that interval is the gene's LOEUF score, 0.65, which puts it in group 2 of 6, group 1 being the genes least tolerant of losing a copy. Missense variants: 1,090 observed, 1,302.1 expected, observed/expected ratio (o/e) 0.84, 90% interval 0.8 to 0.88. Synonymous variants: 525 observed, 521.53 expected, observed/expected ratio (o/e) 1.01, 90% interval 0.94 to 1.08.
Homologues: Orthologues: chimpanzee SCUBE1 (99% identical), macaque SCUBE1 (98% identical), pig SCUBE1 (93% identical), rat Scube1 (92% identical), mouse Scube1 (92% identical), guinea pig SCUBE1 (92% identical), dog SCUBE1 (89% identical), tropical clawed frog scube1 (81% identical), zebrafish scube1 (78% identical). Paralogues in human: SCUBE3 (66% identical), SCUBE2 (65% identical).
Diseases named in the same sentence as SCUBE1 in open-access papers:
SCUBE1 is named in the same sentence as 53 diseases in open-access papers, as found by Europe PMC text mining. Sharing a sentence is not in itself a finding about the gene and the disease. The quoted sentences say what the papers report.
acute coronary syndrome (6 papers, 2018 to 2024). Signs and symptoms related to acute ischemia of the myocardium secondary to coronary artery disease. "A soluble SCUBE1 is released, for instance, from activated platelets and has been described as a clinical biomarker for acute coronary syndrome and ischemic stroke." (PMID 39590217, 2024). "In the previous studies, it was shown that SCUBE-1 concentration was significantly elevated in acute coronary syndrome, myocardial hypoperfusion, acute ischemic stroke, and acute mesenteric ischemia." (PMID 39590594, 2024). "In recent studies, SCUBE1 has been strongly linked to various cardiovascular diseases like acute ischemic stroke, APE, deep vein thrombosis, and acute coronary syndrome." (PMID 38259670, 2024). "Consistently, a 95 kDa proteolytic SCUBE1 fragment is greatly increased in plasma from acute coronary syndrome patients who are experiencing plaque rupture/erosion and subsequent platelet activation; the same fragment is undetectable in healthy people." (PMID 37237303, 2023). "In addition, soluble SCUBE1 is released from activated platelets and can be used as a clinical biomarker for acute coronary syndrome and ischemic stroke." (PMID 37237303, 2023).
breast carcinoma (4 papers, 2022 to 2025). "While increased SCUBE1 expression has been reported in renal cancer and breast cancer, the exact role and relevance of SCUBE1 in various tumor contexts remain relatively underexplored." (PMID 40923331, 2025). "SCUBE1 expression was significantly higher in the serum of HER2-positive breast-cancer patients than that in the HER2-negative phenotype." (PMID 36142489, 2022). "The group also identified a significantly higher expression of SCUBE1 and D-dimer in breast-cancer patients, suggesting SCUBE1 is responsible for hypercoagulability." (PMID 36142489, 2022). "Although the SCUBE1 plasma level is high in the context of some cancers, such as renal and breast cancer, the exact functions of SCUBE1 in cancer cells remain largely unknown and uninvestigated." (PMID 37237303, 2023).
gastric cancer (4 papers, 2017 to 2026). A primary or metastatic malignant neoplasm involving the stomach. "SCUBE1 is a novel mammalian EGF-related protein that has been suggested as a potential new biomarker for gastric cancer." (PMID 41516419, 2026). "Plasma levels of SCUBE1 have been measured as a potential biomarker in several conditions, such as gastric cancer, hypertension, ischaemic heart disease, and stroke (Özkanet al., 2013)." (PMID 28459107, 2017).
ischemic stroke (4 papers, 2021 to 2025). A stroke disorder caused by obstruction of blood flow to the brain, due to thrombotic (local blood clot formation) or embolic (due to a blood clot or other material traveling from another site) event. "SCUBE-1 levels have been found to rise in cases of pulmonary thromboembolism and experimentally induced ischemic stroke." (PMID 40498954, 2025). "SCUBE-1 levels have been shown to increase in experimental ischemic stroke." (PMID 33984895, 2021).
prostate carcinoma (4 papers, 2007 to 2025). A carcinoma that arises from epithelial cells of the prostate gland. "Additionally, Scube1 transcripts were expressed in prostate cancer stromal cells, and were less abundant in cancer associated fibroblasts relative to matched normal prostate fibroblasts." (PMID 17922897, 2007). "Additionally, Scube1 mRNA was expressed in prostate cancer stromal cells, and was downregulated in cancer-associated fibroblasts relative to normal prostate fibroblasts." (PMID 17922897, 2007). "Expression of SCUBE-1 transcripts in prostate cancer stromal cells was encountered in a series analysis of prostate mesenchymal cell gene expressions." (PMID 28379666, 2017). "Scube1 transcripts were identified in all CAFs and NPFs, demonstrating that Scube1 was expressed in prostate cancer stromal cells." (PMID 17922897, 2007). "We showed that Scube1 is expressed in both prostate development and prostate cancer stromal cells, which concurs with the observation that many developmental pathways are involved in tumorigenesis." (PMID 17922897, 2007). "Scube1 is located on human chromosome 22q13, and this region is reported to be deleted in some prostate cancer samples, which supports the notion that Scube1 may function as a tumor suppressor." (PMID 17922897, 2007). "Because Scube1 was specifically expressed in the mesenchyme during development, we examined whether it was present in prostate cancer stroma and whether it was differentially expressed between cancer-associated fibroblasts (CAFs) and normal prostate fibroblasts (NPFs)." (PMID 17922897, 2007). "Scube1 has not been observed in prostate cancer using whole tumor profiling studies, perhaps because it is expressed in a small subset of cells within the tumor that are not well represented in whole tumor gene signatures." (PMID 17922897, 2007).
pulmonary embolism (4 papers, 2017 to 2024). The obstruction of the pulmonary artery or one of its branches by an embolus, sometimes associated with infarction of the lung. "This study aimed to investigate the potential application of plasma signal peptide‐complement C1r/C1s, Uegf and Bmp1‐epidermal growth factor domain‐containing protein 1 (SCUBE‐1) as a biomarker in the diagnosis of pulmonary embolism (PE)." (PMID 36748401, 2023).
COVID-19 (3 papers, 2024 to 2025). A disease caused by infection with severe acute respiratory syndrome coronavirus 2. "Signal peptide-CUB-EGF domain-containing protein 1 (SCUBE-1) is a protein present in platelets and endothelial cells; it is activated by inflammation from COVID-19 and may be associated with COVID-19’s known thrombotic risk." (PMID 39625772, 2024).
Hypertension (3 papers, 2017 to 2024). The presence of chronic increased pressure in the systemic arterial system. "Serum SCUBE-1 levels were found to be higher in patients with hypertension and myocardial infarction compared to normal healthy individuals." (PMID 39590594, 2024). "Plasma sCD40L and SCUBE1 levels are correlated in patients with cardiovascular disease and in in patients with hypertension." (PMID 37237303, 2023). "Moreover, plasma SCUBE1 level is greatly increased due to secretion from platelets and/or ECs in pathologic conditions, making it a possible biomarker of platelet activation in the context of ACS, AIS, hemodialysis or hypertension." (PMID 37237303, 2023).
acute myeloid leukemia (2 papers, 2022 to 2023). Acute myeloid leukemia (AML) is a group of neoplasms arising from precursor cells committed to the myeloid cell-line differentiation. "Xinyue Zhou and Rui Lu discovered that SCUBE1 involving in the initiation and maintenance of MLL-rearranged (MLL-r) acute myeloid leukemia is a novel transcriptional target of HOXA9 and MEIS1, understanding the role of SCUBE1 is contributed to clarify the mechanism of HOXA9/MEIS1in human diseases." (PMID 36376832, 2022).
deep vein thrombosis (2 papers, 2023 to 2024). "The involvement of SCUBE‐1 in thrombosis may indicate its potential for identification of thrombosis‐related clinical condition risks." (PMID 36748401, 2023). "It has been reported that SCUBE‐1 produced in megakaryocytes/platelets contributed to artery thrombosis in the absence of EC‐derived SCUBE‐1 and the its adhesive EGF‐like repeats are essential for crosslinking and stabilizing platelet aggregates during thrombus formation in vivo." (PMID 36748401, 2023).
leukemia (2 papers, 2023 to 2025). A malignant (clonal) hematologic disorder, involving hematopoietic stem cells and characterized by the presence of primitive or atypical myeloid or lymphoid cells in the bone marrow and the blood. "Further analysis is needed to identify all the types of leukemia in which SCUBE1 is aberrantly upregulated." (PMID 37237303, 2023). "In leukemia research, SCUBE1 expression abnormalities have been correlated with poor prognosis." (PMID 40923331, 2025). "Despite the absence of a unique transcriptional regulator for SCUBE1, recent research has shown that in MLL-r leukemia, homeobox A9 (HOXA9) and Meis homeobox 1 (MEIS1) act together to upregulate SCUBE1." (PMID 37237303, 2023). "Moreover, SCUBE1 could be an important target in AML and other types of leukemia due to its regulation by HOXA9, which is overexpressed in a broad range of leukemias." (PMID 37237303, 2023).
polycystic ovary syndrome (2 papers, 2018 to 2022). A disorder that manifests as multiple cysts on the ovaries. "PRECIS: Circulating SCUBE1 levels are elevated in women with Polycystic ovary syndrome compared with those in healthy controls; thus, this protein may be an early biomarker of cardiovascular disease later in life." (PMID 30202624, 2018).
renal carcinoma (2 papers, 2017 to 2025). A carcinoma arising from the epithelium of the renal parenchyma or the renal pelvis. "In the light of these studies, SCUBE-1 may be of significant value as a biomarker in renal cancer, with widespread angiogenesis and thrombosis." (PMID 28379666, 2017).
Sepsis (2 papers, 2021 to 2023). Sepsis is defined as life-threatening organ dysfunction caused by a dysregulated host response to infection. "Since sepsis is a condition caused by severe inflammation that leads to microcirculation disorder, platelet activation, and endothelial damage, we examined the relationship between SCUBE-1 and sepsis disease in our study." (PMID 33578598, 2021). "Nevertheless, there is a need for further studies to examine the specific role of SCUBE-1 in sepsis and sepsis-related mortality." (PMID 33578598, 2021). "The current study aimed to examine the prognostic role of signal peptide-CUB-epidermal growth factor-like domain-containing protein 1 (SCUBE-1) in sepsis and sepsis-related mortality." (PMID 33578598, 2021). "SCUBE-1 is a cell-surface protein that is expressed from platelets and endothelial cells so that we hypotyzed SCUBE-1 may have a role in the sepsis pathway." (PMID 33578598, 2021).
Stroke (2 papers, 2017 to 2023). Sudden impairment of blood flow to a part of the brain due to occlusion or rupture of an artery to the brain. "As such, the concentration of SCUBE1 in plasma can be considered an independent indicator of stroke severity based on the National Institute of Health Stroke Scale (β = 3.18, p < 0.001)." (PMID 37237303, 2023).
acute kidney injury (1 paper, 2023). Sudden and sustained deterioration of the kidney function characterized by decreased glomerular filtration rate, increased serum creatinine or oliguria. "Given the susceptibility of Δ2 mutants after I/R injury and the novel BMP7-enhancing effects of upregulated SCUBE1 in response to I/R stress, targeting SCUBE1 might be a feasible treatment strategy for acute kidney injury." (PMID 37237303, 2023).
autoimmune disease (1 paper, 2024). A disorder resulting from loss of function or tissue destruction of an organ or multiple organs, arising from humoral or cellular immune responses of the individual to their own tissue constituents. "However, SCUBE1, IL-6, and IMA can be raised in other pathologies, especially chronic inflammatory and autoimmune diseases." (PMID 39519217, 2024).
coagulopathy (1 paper, 2019). "As coagulopathy in isolated TBI is associated with increased mortality, D-Dimer, thrombospondin-1, and SCUBE1 could be important prognostic indicators in sTBI." (PMID 31105646, 2019).
cognitive deficits (1 paper, 2025). "Additional genes from Regions 2 and 3 (PHF21B, SULT4A1, SCUBE1, and NUP50) we speculate that they may further contribute to cognitive deficits, neurodevelopmental features, and growth abnormalities." (PMID 40429797, 2025).
diabetes (1 paper, 2024). "Studies have found that SCUBE1 levels are significantly elevated in the serum of diabetic patients, which may be associated with chronic inflammatory responses induced by diabetes." (PMID 39543487, 2024). "The protein encoded by SCUBE1 is associated with angiogenesis and cell signaling, potentially influencing the function of vascular endothelial cells, thus playing a role in vascular changes and wound healing in diabetes." (PMID 39543487, 2024).
diabetic foot ulcers (1 paper, 2024). "This is the first report identifying SCUBE1 and RNF103-CHMP3 as therapeutic targets for diabetic foot ulcers (DFU)." (PMID 39543487, 2024). "Our data showed that compared to non-foot ulcer samples (Non), the expression levels of SCUBE1 and RNF103-CHMP3 were elevated in diabetic foot ulcer (DFU) samples." (PMID 39543487, 2024).
hemorrhagic fever (1 paper, 2017). An infectious disease caused by certain viruses or bacteria that can damage the walls of tiny blood vessels, making them leak, and can hamper the blood's ability to clot and cause severe, life-threatening illness. "SCUBE-1 has also been described as a valuable biomarker in determining severity and prognosis of disease in patients with Crimean-Congo hemorrhagic fever." (PMID 28379666, 2017).
hyperandrogenism (1 paper, 2018). Excessive secretion of androgens from the adrenal glands or gonads. "Taken together, these findings suggest that increased SCUBE1 level is an independent contributor to an increased risk of cardiovascular events in women with PCOS, regardless of other traditional risk factors, such as obesity, insulin resistance, and hyperandrogenism." (PMID 30202624, 2018). "Serum SCUBE1 levels in patients with PCOS stratified according to hyperandrogenism were not statistically different from one another (5.8±2.8 ng/mL in normoandrogenic PCOS vs. 5.9±3.1 ng/mL in hyperandrogenic PCOS, p=0.91)." (PMID 30202624, 2018).
hypertensive nephropathy (1 paper, 2025). Kidney damage that results from chronically elevated blood pressure; complications include glomerular damage resulting in proteinuria and hematuria. "As a result,hypertensive retinopathy may show more pronounced vascular changes and damage.Similarly, given the complex structure and functionality of the kidneys,hypertensive nephropathy may affect SCUBE-1 expression and function throughmultiple mechanisms." (PMID 39867205, 2025).
ischemia (1 paper, 2024). A hypoperfusion of the BLOOD through an organ or tissue caused by a PATHOLOGIC CONSTRICTION or obstruction of its BLOOD VESSELS, or an absence of BLOOD CIRCULATION. "Maternal serum SCUBE-1, which is a novel marker of ischemia, might have a potential role in diagnosis and screening of PE." (PMID 39590594, 2024).
liver cancer (1 paper, 2023). An epithelial or non-epithelial malignant neoplasm that arises from the liver. "The following genes were upregulated in liver cancer: CTB-31N19.5 (methyl transferase like 9), BAHCC1 (Bromo Adjacent Homology domain and Coiled-Coil Containing 1), SCUBE1 (Signal Peptide, CUB Domain and EGF Like Domain Containing 1)." (PMID 37744383, 2023).
multiple myeloma (1 paper, 2022). "Another study demonstrated that the lower expression of SCUBE1 in multiple myeloma patients could be responsible for an increased risk for arterial thrombosis, although the association remains unestablished." (PMID 36142489, 2022). "The study concluded that lower expression of SCUBE1 may be possible due to defective platelets or increased TNF-α expression in multiple myeloma patients." (PMID 36142489, 2022).
preeclampsia (1 paper, 2025). Preeclampsia is a hypertensive disorder of pregnancy that is characterized by new-onset hypertension with proteinuria presenting after 20 weeks of gestation, and depending on mild or severe forms may initially present with severe headache, visual disturbances, and hyperreflexia. "Our previous study demonstrated that the level of SCUBE-1, a new marker of oxidative stress, was increased in preeclampsia." (PMID 41300915, 2025).
pulmonary hypertension (1 paper, 2023). Increased pressure within the pulmonary circulation due to lung or heart disorder. "Therefore, SCUBE1 downregulation in the context of pulmonary hypertension could be a specific biomarker of disease." (PMID 37237303, 2023).
thrombotic disease (1 paper, 2024). The formation of a blood clot in the lumen of a vessel or heart chamber; causes include coagulation disorders and vascular endothelial injury. "The SCUBE-1 is highly expressed in vascular endothelial cells and platelets and is known to increase in thrombotic diseases with platelet and endothelial activation." (PMID 39625772, 2024). "Unlike other members of the SCUBE gene family, SCUBE-1 tends to cause inflammation and thrombosis and can be evaluated as a prognostic factor in platelet activation and thrombotic diseases." (PMID 39625772, 2024).
Venous thrombosis (1 paper, 2023). Formation of a blood clot (thrombus) inside a vein, causing the obstruction of blood flow. "In addition, mutation of SCUBE‐1 gene increases the risk of venous thrombosis." (PMID 36748401, 2023).
cancer (5 papers, 2007 to 2025). A tumor composed of atypical neoplastic, often pleomorphic cells that invade other tissues. "Besides, Tumor Immune single-cell Hub (TISCH), a single-cell sequencing database, showed that SCUBE1 expression was higher in CAFs than that in cancer cells in most cancers." (PMID 36348351, 2022). "TISCH was used to analysed the SCUBE1 mRNA in different cell populations in kinds of cancers." (PMID 36348351, 2022). "SCUBE-1 has been investigated as a marker in non-cancer diseases." (PMID 28379666, 2017). "SCUBE-1, a cell surface protein, has been investigated in various types of cancer and non-cancer diseases." (PMID 28379666, 2017).